BDNF (brain derived neurotrophic factor)
Diseases named in the same sentence as BDNF in open-access papers (continued):
Sharing a sentence is not in itself a finding about the gene and the disease.
Anxiety (continued). "Second, reduction of neurogenesis- and anxiety-related neurotransmitters such as BDNF, 5HT1A and Drd2 in the PFC was observed." (PMID 37407491, 2023). "The results showed that exercise plus fluoxetine decreased anxiety-like behavior, improved fear extinction, and increased BDNF changes in female rats." (PMID 36647145, 2023). "In mice, social isolation is known to increase anxiety-related behavior and depressive states, to elevate corticosterone concentrations and reduce levels of brain-derived neurotrophic factor (BDNF)." (PMID 37953247, 2023). "Previous studies have found that probiotic supplementation in animal models can improve social deficits in mice with ASD and improve anxiety-like behavior and elevate hippocampal BDNF levels in mice with low-grade intestinal inflammation." (PMID 37007488, 2023). "The inhibition of miR-142-5p exhibited increased Npas4 and BDNF expressions and decreased anxiety-like behaviors and memory deficits." (PMID 37340171, 2023). "For instance, the ability of some gut bacterial strains to induce anxiety-like behaviors and alter the expression of brain derived neurotrophic factor (BDNF) and GABA receptor subunits in the HPC depends on vagal afferents." (PMID 37131071, 2023). "In contrast, hippocampal BDNF overexpression significantly diminished stereotypical behavior and anxiety; these alterations were accompanied only by higher hippocampal DA receptor D1 mRNA levels." (PMID 37239153, 2023). "Recent studies have shown that regulating FGFR can affect BDNF expression and that the BDNF-TrkB signaling pathway plays an important role in anxiety." (PMID 38075046, 2023). "Defects in the mechanism of pro-BDNF conversion to BDNF, or imbalances between these two forms, have been correlated with impaired cognitive function, psychiatric disorders, and anxiety symptoms." (PMID 37958943, 2023). "Neurotrophin and neurotransmitter receptors: Neurotrophic factor such as brain-derived neurotrophic factor (BDNF) and anxiety-related neurotransmitters such as serotonin receptor 5HT1A, dopamine receptor Drd2 in the PFC were examined." (PMID 37407491, 2023). "Several lines of evidence point to the need to explore the relationship between anxiety and peripheral brain-derived neurotrophic factor (BDNF) levels." (PMID 38055476, 2023). "This interaction can concurrently stimulate CREB/BDNF to modify brain synaptic plasticity and participate in anxiety regulation." (PMID 38075046, 2023). "Several studies have reported the involvement of Hes in the CREB/BDNF pathway in improving memory function, anxiety in diabetes, and pentylenetetrazole-induced convulsions." (PMID 37663268, 2023). "Compared with wild-type (WT) controls, diminished activity-dependent BDNF signaling similarly induced anxiety-like behaviors in male and female mice." (PMID 37205980, 2023). "Recently, it was shown that i.c.v.-injected BDNF can dose-dependently decrease anxiety-like behavior in mice." (PMID 37239153, 2023). "Gestational stress increases the expression of DNMTs and DNA methylation of BDNF, thereby inducing depressive-like and anxiety-like phenotypes by downregulation of BDNF expression in the hippocampus of the offspring." (PMID 36590248, 2023). "Deletion of the brain-derived neurotrophic factor (BDNF) gene in specific brain regions leads to impaired GABAergic transmission and increased anxiety." (PMID 37598204, 2023). "In summary, we performed the first case-controlled and prospective study combining serum BDNF and anxiety-related variables to explore predictive indicators of changes in somatic symptoms in PD patients." (PMID 37533888, 2023). "The deficiency of SCFAs exaggerates neuroinflammation by increasing IL-1β and IL-6 expression in the hippocampus, thereby promoting anxiety through inhibiting BDNF-GABA signal pathway." (PMID 37273529, 2023).
Anxiety (continued). "We chose the PHQ-15 changes as the dependent variable to explore the predictive roles of baseline independent variables, i.e., serum BDNF levels and anxiety-related variables." (PMID 37533888, 2023). "ROS induces synaptic dysfunction by suppressing the BDNF-synapsin I/CREB pathway to aggravate anxiety." (PMID 37273529, 2023). "Changes in NGF and BDNF levels in serum have been detected in patients with neurodegenerative and psychiatric diseases, anxiety, mood disorders, and stress but the importance of distinguishing mature and precursor NTs has been pointed out only recently." (PMID 37175781, 2023). "This prompted us to evaluate the efficacy of treatment with BDNF-releasing devices on behavioral parameters like anxiety-, learning-, and memory-related behavior which was performed using a separate cohort of animals (cohort 3)." (PMID 37596686, 2023). "Its expression is negatively correlated with BDNF expression in hippocampal neurons and impairs neuronal development and synaptic plasticity, resulting in anxiety-like behavior." (PMID 38075046, 2023). "BDNF has a protective effect on brain health, and levels are reduced in patients with depression and anxiety." (PMID 37468978, 2023). "The present study confirmed that SPS is able to induce anxiety-like behavior and other PTSD-associated alterations such as BDNF changes and fear conditioning and extinction impairment in female rats." (PMID 36647145, 2023). "While young adult rats showed an increase in BDNF expression, they also demonstrated high-anxiety behaviors in the open field test compared with controls." (PMID 35998298, 2023). "According to previous reports, the rat anxiety model is obtained after prolonged low‐current shock or forced swimming, and then the anxiety level is reduced by injecting BDNF into the spinal cord of anxious rats." (PMID 37118929, 2023). "Activation of σ-1R has been reported to reduce memory impairment and anxiety-like behaviors induced by single-prolonged stress (SPS) through reversing the downregulated brain derived neurotrophic factor (BDNF) related signaling pathways." (PMID 37340171, 2023). "The BDNF genotype has been reported to affect anxiety-related personality traits and resting CBF in the frontolimbic neurocircuitry of healthy people." (PMID 36761347, 2023). "To further examine diminished activity-dependent BDNF signaling similarly induces anxiety-like behaviors in males and females, we performed an elevated plus maze (EPM) test to examine anxiety-like behaviors under a stress condition." (PMID 37205980, 2023). "Further research was focused on the traditional ERK/CREB/BDNF signal transduction pathway, which has been reported to be related to the pathogenesis of anxiety." (PMID 36936941, 2023). "As for the further investigation the detailed mechanisms of anxiety-like behavior accompanied with downregulation of brain-derived neurotrophic factor in F1 female mice should be elucidated." (PMID 37407491, 2023). "Compared with nonalcohol‐preferring rats, alcohol‐preferring rats showed significant anxiety behavior, and the activity of BDNF and its downstream target molecules regulated the expression of mRNA and protein levels of cytoskeletal proteins." (PMID 37118929, 2023). "Still in healthy participants, plasma BDNF levels were confirmed to be significantly correlated with harm avoidance, a well-known anxiety-related personality trait." (PMID 35815047, 2022). "Genome-wide association studies pointed for the involvement of the Val66Met (rs6265) in anxiety and response to stress, with Val/Val homozygotes that show increased anxiety, suggesting a role of BDNF in gene-environment interactions." (PMID 36034425, 2022). "Specifically, female rats with anxiety-like behavior had increased BDNF concentration in the HIP and cortex and decreased neuropeptide Y as well as parvalbumin interneurons in the CA1 region." (PMID 36159923, 2022).
Anxiety (continued). "One possible mechanism leading to anxiety-like behavior involves the BDNF/TrkB system in both male and female rodents." (PMID 36159923, 2022). "SPF mice receiving cocktail of neomycin, bacitracin and pimaricin showed GD to be accompanied by increased exploratory behavior, reduced anxiety, and altered BDNF levels in the hippocampus and amygdala." (PMID 36611848, 2022). "Mutant mouse lines with reduced levels of BDNF show increased or unaltered anxiety, and increasing BDNF levels also increases anxiety." (PMID 35140204, 2022). "Histochemical and biochemical analyses identified altered cortical and hippocampal neuron development and deficits in BDNF-TrkB signaling; anxiety-like levels were partially rescued by chronic administration of the BDNF mimetic 7,8-DHF to cKO mice." (PMID 35140204, 2022). "The pharmacological rescue experiments indicate that alterations in BDNF signaling system contribute only partially to the low-anxiety phenotype of cKO animals." (PMID 35140204, 2022). "Administration of a probiotic such as Bifidobacterium longum normalized the hippocampal BDNF levels and reduced the inflammation-induced anxiety-like behavior in animal models." (PMID 35456041, 2022). "GF zebrafish have abnormal anxiety-related and locomotor behaviors that can be attenuated by probiotic administration, an intervention that also influences shoaling behavior via brain-derived neurotrophic factor (BDNF) and serotonin signaling." (PMID 36318534, 2022). "BPA dysregulates Rsg4 transcription in cortical pyramidal neurons, leading to BPA-mediated abnormal synaptic formation, anxiety and mild cognitive dysfunction via regulation of BDNF/NTRK2 signaling." (PMID 35781563, 2022). "Naringenin has been shown to improve depressive- and anxiety-like behaviors in mice exposed to repeated hypoxic stress by modulating oxido-inflammatory mediators and NF-κB/BDNF expression." (PMID 36499295, 2022). "They reduces anxiety by increasing hippocampal BDNF expression, along with elevated levels of pAkt in the hippocampus and cortex." (PMID 36499295, 2022). "4-Hydroxycinnamic acid (P-coumaric acid) promotes hippocampal neurogenesis, improves cognitive functions, and reduces anxiety in post-ischemic stroke rats by activating BDNF/TrkB/AKT signaling pathway." (PMID 36225186, 2022). "In the present study, we report on the association among pandemic-related stress during pregnancy, maternal BDNF methylation, and postnatal anxiety symptoms." (PMID 35911240, 2022). "Recent studies showed that miR-206 targets BDNF, which regulates anxiety-related behaviors and neuropathic pain induced by chronic contraction injury." (PMID 35781287, 2022). "We compared Kidins220lox/lox and Kidins220 cKO animals and identified changes of brain neuron morphology and reduced anxiety, partially ascribable to impairments of the BDNF/TrkB axis." (PMID 35140204, 2022). "Studies showed that chronic infection can lead to the reduced BDNF expression and increased anxiety-like behaviors." (PMID 35967771, 2022). "Minocycline treatment attenuated LPS-induced locomotor deficits and anxiety-like behaviour in rats and decreased phosphorylated tau protein levels, but it increased the expressions of the BDNF/CREB proteins in the mPFC." (PMID 36362262, 2022). "In restraint-stressed rats, wheel-running improved anxiety-like behavior, depressive-like behavior, and memory impairment, and was accompanied by expression of brain-derived neurotrophic factor (BDNF) in the hippocampus." (PMID 36160683, 2022). "The sand rats that showed diminished BDNF circadian rhythms also demonstrated higher blood glucose and insulin levels, as well as significantly higher anxiety- and depressive-like behaviors compared to animals acclimated to neutral photoperiod." (PMID 35165331, 2022).
Anxiety (continued). "For instance, in some studies using disease or stress-induced rodents, bifidobacterial strains reduced anxiety-like behaviors by increasing brain-derived neurotrophic factor (BDNF) expression in the hippocampus." (PMID 35918353, 2022). "Similarly, in a knock-in mouse line containing the variant BDNF, it has been previously shown that the Met allele is associated with decreased activity-dependent BDNF secretion from neurons in addition to increased anxiety-related behaviors and impaired fear extinction." (PMID 36008382, 2022). "The administration of the single strain B. longum NCC3001 effectively treated anxiety, upregulating the expression of BDNF in the hippocampus." (PMID 35204119, 2022). "In mice injected with human BDNF Val66Met, increased anxiety-like behaviors during the estrous phase are observed." (PMID 36699021, 2022). "As a novel antidepressant, agomelatine reduces anxiety-like behaviors and upregulates BDNF levels in the dentate gyrus." (PMID 36699021, 2022). "B. longum supplementation reversed anxiety-like behavior and BDNF levels in brain samples of mice co-morbid with infectious colitis." (PMID 36611848, 2022). "Minocycline, in a dose-dependent manner, improved locomotor deficits and anxiety-like behaviour, decreased phosphorylated tau proteins, and upregulated BDNF/CREB protein expressions in the mPFC of LPS rats." (PMID 36362262, 2022). "The amygdala and hippocampus of GF mice showed lower concentrations of 5-HT, BDNF, and the specific 5-HT1A receptor, all of which are associated with anxiety- and depressive-like behavior." (PMID 35456041, 2022). "The altered expression of four anxiety-related genes, c-Fos, Adora2a, BDNF, and AGRN were additionally confirmed by RT-qPCR." (PMID 35491423, 2022). "Recently, AP-1 was observed to have a role in fluoxetine response in a murine model of heightened anxiety, and was also found to be activated by other factors such as BDNF, which is itself a factor influencing the response to different ATD treatments." (PMID 36386175, 2022). "Some studies have also found that thymol reduces depressive symptoms (via the upregulation of BDNF levels), restores anhedonia and short-term memory, and improves anxiety." (PMID 36499295, 2022). "Application of miR-137 antagomir in the amygdala decreased BDNF levels and improved anxiety-like behavior following alcohol consumption in rats." (PMID 35916975, 2022). "Although there is no definitive explanation for the relationship between these genes and anxiety, the discovery of BDNF Val66Met continues to hold promise for the development of effective drugs that target these genes for the treatment of anxiety disorders." (PMID 35814950, 2022). "The expression of brain-derived neurotrophic factor and neuronal nitric oxide synthase, important regulators of anxiety-like behaviors, was low in db/db mice, but TGF-β2 infusion did not affect their expression." (PMID 36091357, 2022). "Catechins mitigate anxiety and provide mood-related benefits by modulating BDNF levels and the pro-BDNF and monoaminergic signaling pathways." (PMID 36014776, 2022). "The increased level of BDNF (brain derived neurotrophic factors) helps to reverse anxiety, depression and mood swings, which is related to sleep disturbances." (PMID 35755917, 2022). "The cAMP response element-binding (CREB) protein regulates the transcription and subsequent expression of BDNF, and it is also involved in locomotion and anxiety-like behaviour." (PMID 36362262, 2022). "Another study suggested that BDNF rs6265 had a significant interaction effect with Catechol-O-methyltransferase gene (COMT) polymorphism to neuroticism and anxiety trait in PD patients, instead of healthy control subjects." (PMID 35815047, 2022). "We have previously found that following UCMS, adolescent mice exhibit a high level of anxiety and a reduction in hippocampal brain-derived neurotrophic factor (BDNF) levels." (PMID 35563336, 2022).
Anxiety (continued). "It has been reported that the reduction of miR-124a expression in the hippocampal dentate gyrus leads to decreased anxiety-like behavior, which is inversely correlated with the expression of its target gene, BDNF." (PMID 35916975, 2022). "In the social deprivation stress-triggered anxiety- and depressive-like mice, BDNF levels are reduced in the brain." (PMID 35996194, 2022). "In the present study, we report data on the association among pandemic-related stress during pregnancy, maternal BDNF methylation, and postnatal anxiety symptoms." (PMID 35911240, 2022). "In a rat model of sub-chronic stress-induced anxiety, saffron had protective effects on anxiety via downregulating serum cortisol level and upregulating the gene expression of BDNF in hippocampus." (PMID 36358502, 2022). "The inhibition of miR-142-5p in these rats reduced anxiety-like behaviors and enhanced Npas4 and BDNF expressions." (PMID 35916975, 2022). "Bacterial strains exert positive effects on memory and anxiety through their metabolites such as SCFAs and brain-derived neurotrophic factor (BDNF) that arbitrate the interaction between the gut microbiota and the central nervous system." (PMID 35269766, 2022). "Correlation between the performance in the anxiety/cognition-related tasks and hippocampal mRNA levels of BDNF and Syt-1 [r (p)]." (PMID 36570704, 2022). "In open-field and sucrose preference tests, they show that both live and heat-killed PS23 are able to reverse chronic corticosterone-induced anxiety- and depressive-like behaviors and reverse corticosterone-reduced BDNF protein levels in the hippocampus." (PMID 34356624, 2021). "Spearman correlation analysis of the anxiety score was conducted with levels of NP, monoamine neurotransmitters, and BDNF." (PMID 34046258, 2021). "With regard to the BDNF levels and immune cell numbers based on anxiety scores in the different chronic pain diseases, a significant difference was found exclusively in the level of free BDNF in OA patients." (PMID 33915758, 2021). "Our finding of elevated maternal BDNF was exclusive to the mothers of boys reporting higher anxiety symptoms." (PMID 33462179, 2021). "Here, we demonstrate that systemic immunosuppression failed to attenuate substrain dissimilarities in brain weight, soluble tau/phospho-tau, BDNF expression, or anxiety-related tasks." (PMID 33472690, 2021). "Pre-weaning enrichment was also able to rescue animals from anxiety-like behaviors in adulthood induced by post-weaning maternal separation stress, while increasing BDNF content in the basolateral amygdala." (PMID 33578758, 2021). "Telmisartan treatment also increased the level of BDNF in stressed animals and reduced anxiety-like behavior in the elevated plus-maze." (PMID 34451870, 2021). "The administration of anti-TNF-a rescued the anxiety-like symptoms though expression of the brain-derived neurotrophic factor remained low." (PMID 33498197, 2021). "On the other hand, mice overexpressing BDNF in the forebrain, including the hippocampus and cortex, also displayed higher anxiety-like scores compared with wild-type littermate controls." (PMID 34769417, 2021). "Further, studies of germ-free mice have reported increased anxiety and reduced neurotrophic factors such as brain-derived neurotrophic factor (BDNF)." (PMID 35010939, 2021). "Several studies demonstrated that gut dysbiosis correlates with reduced expression of BDNF, which alters cognitive function and triggers anxiety-like behavior in germ-free animals, supporting a role of BDNF in the gut–brain axis." (PMID 32300799, 2021). "Over the past decade, BDNF has been shown to regulate stress- and anxiety-related behaviors while playing a critical role in the fear circuit." (PMID 33643051, 2021). "Two studies reported a relationship between cord blood serum BDNF and maternal anxiety symptoms, again with contrasting findings." (PMID 33462179, 2021).